RIN2 (Ras and Rab interactor 2)
Description:
Ras effector protein. May function as an upstream activator and/or downstream effector for RAB5B in endocytic pathway. May function as a guanine nucleotide exchange (GEF) of RAB5B, required for activating the RAB5 proteins by exchanging bound GDP for free GTP.
Synonyms: RASSF4; MACS
Tractability: PROTAC: ubiquitination databases record sites on it.
Gene: Protein-coding gene on chromosome 20 (19,757,606 to 20,003,571, forward strand). Ensembl gene ENSG00000132669.
Subcellular location: Cytoplasm
Subcellular location (Human Protein Atlas): Cytosol; Golgi apparatus; Nucleoli
Pathways (Reactome):
Vesicle-mediated transport: RAB GEFs exchange GTP for GDP on RABs
Gene Ontology:
Molecular function: GTPase regulator activity; guanyl-nucleotide exchange factor activity; small GTPase binding
Biological process: positive regulation of endothelial cell migration; positive regulation of endothelial cell-matrix adhesion; positive regulation of vasculogenesis; small GTPase-mediated signal transduction; signal transduction; vesicle-mediated transport
Cellular component: cytosol; endocytic vesicle; cytoplasm
Genetic constraint (gnomAD): Loss-of-function variants: 33 observed, 69.28 expected, observed/expected ratio (o/e) 0.48, 90% interval 0.36 to 0.64. The upper end of that interval is the gene's LOEUF score, 0.64, which puts it in group 2 of 6, group 1 being the genes least tolerant of losing a copy. Missense variants: 1,072 observed, 1,155.3 expected, observed/expected ratio (o/e) 0.93, 90% interval 0.88 to 0.98. Synonymous variants: 461 observed, 460.05 expected, observed/expected ratio (o/e) 1, 90% interval 0.93 to 1.08.
Gene-disease validity (ClinGen):
ClinGen rates the evidence that RIN2 causes each of these diseases.
RIN2 syndrome (autosomal recessive): Definitive. RIN2 syndrome, formerly known as macrocephaly, alopecia, cutis laxa and scoliosis (MACS) syndrome, is a very rare inherited connective tissue disorder characterized by macrocephaly, sparse scalp hair, soft-redundant and hyperextensible skin, joint hypermobility, and scoliosis.
Homologues: Orthologues: chimpanzee RIN2 (99% identical), macaque RIN2 (99% identical), rabbit RIN2 (94% identical), dog RIN2 (93% identical), rat Rin2 (92% identical), mouse Rin2 (92% identical), guinea pig RIN2 (86% identical), tropical clawed frog rin2 (67% identical), zebrafish rin2a (53% identical), zebrafish rin2b (44% identical), Drosophila melanogaster spri (25% identical), Caenorhabditis elegans rin-1 (24% identical), and 2 more. Paralogues in human: RIN3 (32% identical), RIN1 (27% identical), RINL (17% identical), GAPVD1 (16% identical), VPS9D1 (12% identical), RABGEF1 (11% identical).
Diseases named in the same sentence as RIN2 in open-access papers:
RIN2 is named in the same sentence as 24 diseases in open-access papers, as found by Europe PMC text mining. Sharing a sentence is not in itself a finding about the gene and the disease. The quoted sentences say what the papers report.
alopecia (4 papers, 2013 to 2023). Hair loss usually from the scalp. "Biallelic defects in RIN2 are associated with MACS syndrome, a condition characterized by macrocephaly, alopecia, cutis laxa, and scoliosis, as well as with RIN2 syndrome, a related connective tissue disorder presenting similar symptoms." (PMID 37207166, 2023).
colorectal cancer (1 paper, 2023). A primary or metastatic malignant neoplasm that affects the colon or rectum. "Furthermore, RIN2 has been identified as a signature gene that can be used to evaluate the clinical prognosis of patients with colorectal cancer, enabling more personalized diagnosis and treatment of the disease." (PMID 37207166, 2023).
ovarian carcinoma (1 paper, 2025). A malignant neoplasm originating from the surface ovarian epithelium. "A multivariate analysis revealed that, after controlling for TGFB2 expression, four genes (CLIC3, ANPEP/LAP1, RIN2, and EMP1) showed negative correlations between mRNA expression and OS across all expression levels in an ovarian cancer cohort." (PMID 41465326, 2025).
Overgrowth (1 paper, 2022). Excessive postnatal growth which may comprise increased weight, increased length, and/or increased head circumference. "For RIN2 (Ras and Rab interactor 2), Enrichr-Jensen DISEASES analysis associated RIN2 with gingival overgrowth, and literature studies associate it with endocytosis and bone formation." (PMID 36005137, 2022).
prostate tumors (1 paper, 2013). "We also queried specific ucRNAs and found, for example, that uc.454 + A, which was the most down-regulated ucRNA in prostate tumors, was predicted to directly interact with Ras signaling pathway-related transcripts, like RIN2 and RAB37." (PMID 23409773, 2013).
triple-negative breast carcinoma (1 paper, 2025). An invasive breast carcinoma which is negative for expression of estrogen receptor (ER), progesterone receptor (PR), and human epidermal growth factor receptor 2 (HER2). "Recent research has also implicated RIN2 in the progression of triple-negative breast cancer." (PMID 41465326, 2025).
cancer (3 papers, 2021 to 2025). A tumor composed of atypical neoplastic, often pleomorphic cells that invade other tissues. "RIN2 is crucial for regulating endosomal trafficking, a process that has significant implications for cancer-related signaling pathways and receptor trafficking." (PMID 41465326, 2025). "The role of RIN2 in cell adhesion may contribute to cancer metastasis." (PMID 41465326, 2025). "Although RIN2 has not been studied in terms of its role in PCa, as one of DNA damage and repair related gene sets, this gene has been investigated in colorectal and esophageal cancers." (PMID 35053153, 2021).
tumor (2 papers, 2023 to 2025). "RIN2 plays a role in angiogenesis, which is a vital process for tumor growth and metastasis." (PMID 41465326, 2025).
infection (1 paper, 2022). The state of being infected such as from the introduction of a foreign agent such as serum, vaccine, antigenic substance or organism. "For example, the subset of proteins ATMCB1, VPS36, LRS1, SH3P2 and RIN2 were up-regulated during infection with S. sclerotiorum and B. cinerea, and could be novel ubiquitin- and/or AIM- binding receptors with functions in immunity." (PMID 35635102, 2022).
neurodegenerative disease (1 paper, 2025). A disorder of the central nervous system characterized by gradual and progressive loss of neural tissue and neurologic function. "KEGG pathway analysis implicated neurodegenerative diseases pathways and highlighted target genes associated with long-term depression signaling and tryptophan metabolism, including RIN2, TCF7L1, DDIT4, and KLF11." (PMID 41009397, 2025).
RIN2 also shares sentences with these, for which no sentence is quoted: scoliosis (3 papers); connective tissue disorder (2); cutis laxa (2); Macrocephaly (2); cardiomyopathy (1); dementia (1); dilated cardiomyopathy (1); dysplasia (1); esophageal cancer (1); esophageal tumor (1); MACS syndrome (1); Obesity (1); RIN2 syndrome (1); testicular cancer (1).